REN (renin)
Diseases named in the same sentence as REN in open-access papers (continued):
Sharing a sentence is not in itself a finding about the gene and the disease.
obstructive jaundice (2 papers, 2011 to 2015). A finding indicating increased bilirubin levels in the blood and urine, due to intrahepatic or extrahepatic obstruction of the biliary system. "Poo found elevated renin and angiotensin II at 1 week after establishment of obstructive jaundice in rats." (PMID 22204383, 2011).
osteoarthritis (2 papers, 2023 to 2026). A noninflammatory degenerative joint disease occurring chiefly in older persons, characterized by degeneration of the articular cartilage, hypertrophy of bone at the margins and changes in the synovial membrane. "The implication of the tissue-localized renin-angiotensin system (RAS) in the pathogenesis of osteoarthritis (OA) has been documented in the last decades." (PMID 37725260, 2023).
ovarian failure (2 papers, 2022 to 2024). "Studies have suggested that estrogen replacement therapy can modulate the renin–angiotensin–aldosterone system and potentially lower blood pressure in patients with ovarian insufficiency." (PMID 39119483, 2024).
ovarian hyperstimulation syndrome (2 papers, 2022). A complication of ovulation induction in infertility treatment. "High renin activity was found in both follicular fluid and plasma in patients with OHSS and was found to be directly associated with the severity of ovarian hyperstimulation syndrome." (PMID 36619582, 2022).
overnutrition (2 papers, 2014 to 2017). An imbalanced nutritional status resulting from excessive intake of nutrients. "Here we investigated the cardioprotective effects of linagliptin on development of DD in western diet (WD)-fed mice, a clinically relevant model of overnutrition and activation of the renin-angiotensin-aldosterone system." (PMID 28476142, 2017).
pancreatitis (2 papers, 2015 to 2024). Inflammation of the pancreas. "Major components of the renin-angiotensin-aldosterone system (angiotensinogen and angiotensin receptors 1 and 2) were upregulated in rat pancreatic acinar cells during pancreatitis and treatment with the angiotensin receptor antagonist losartan inhibited the acinar digestion enzyme secretion." (PMID 38510657, 2024).
pregnancy hypertension (2 papers, 2023). "Although previous studies have indicated that the sensitivity of renin and aldosterone to salt are blunted in pregnancy, differences in the salt–aldosterone relationships in pregnancy hypertension versus normotensive pregnancies are not well understood." (PMID 37628909, 2023). "These effectors are reduced in patients with pregnancy hypertension, creating an opportunity to define the features of the renin–angiotensin–aldosterone system (RAAS) that are characteristic of this disorder." (PMID 37628909, 2023). "Differences in sodium, renin, and aldosterone relationships in pregnancy hypertension vs. normotensive are not well understood." (PMID 38001956, 2023).
pseudohypoaldosteronism (2 papers, 2023 to 2025). An inherited or acquired disorder of electrolyte metabolism, characterized by the inability of the renal tubules to respond to aldosterone. "On the other hand, in presence of normal or elevated aldosterone levels and in the absence of cortisol deficiency, normal or low renin levels will not exclude a condition of pseudohypoaldosteronism." (PMID 36763264, 2023).
type 2 diabetic nephropathy (2 papers, 2015 to 2018). "The aim of the double-blind study performed in parallel at two centers was to determine whether albuminuria was reduced further when atrasentan was administered at two different doses, with inhibitors of the renin-angiotensin system, to patients with type 2 diabetic nephropathy." (PMID 25966344, 2015).
urolithiasis (2 papers, 2025). Stone(s) within the urinary tract. "Contemporary literature suggests 2 distinct clinical patterns: acute-onset flank pain with hematuria mimicking urolithiasis (60–70% cases), and “hypertensive crisis-first” presentations due to secondary renin-angiotensin-aldosterone system activation (30–40% cases)." (PMID 40629625, 2025). "Naringenin also demonstrated moderate to strong binding affinity with other urolithiasis and renal protection-related targets, including glycolate oxidase (−8.3 kcal/mol), a key enzyme in oxalate synthesis, and ACE (−7.9 kcal/mol), involved in the renin–angiotensin system." (PMID 40573268, 2025).
Vasovagal syncope (2 papers, 2015 to 2025). A vasovagal episode or vasovagal syncope is the most common form of reflex syncope. "A previous study has demonstrated that 25% of normal subjects who develop vasovagal syncope after upright tilt have reduced renin activity both in magnitude and duration compared with the normal response." (PMID 26053073, 2015). "Similar RAAS dysfunction has also been reported in children with vasovagal syncope (VVS), characterized by slightly increased renin and Ang II levels, but decreased aldosterone levels." (PMID 40453223, 2025).
venous congestion (2 papers, 2020 to 2022). "We and others have demonstrated that renal venous congestion is associated with activation of the renin–angiotensin system (RAS)." (PMID 35185611, 2022). "In turn, renal venous congestion affects the activation of the sympathetic nervous system and the renin-angiotensin-aldosterone system; it also induces the baroreceptor-associated, neural reflex and natriuretic peptide pathways." (PMID 33147835, 2020).
vitamin A deficiency (2 papers, 2023 to 2025). Deficiency of vitamin A due to malnutrition, malabsorption, or dietary lack. "It was found that LRAT may be a critical biomarker of vitamin A deficiency in target organs and may regulate blood pressure through affecting renin angiotensin system biomarkers." (PMID 36869404, 2023).
Zinc deficiency (2 papers, 2021 to 2023). A deficiency of the essential metal Zinc; an essential cofactor for many enzymes. "A recent review of the literature suggests that zinc deficiency in HF may result from a reduced intake or a diminished absorption of the micronutrient, a strong inflammatory state, the hyper-activity of the renin–angiotensin–aldosterone axis, and hyperzincuria due to HF medications." (PMID 37110221, 2023).
Acidosis (1 paper, 2021). Abnormal acid accumulation or depletion of base. "Acidosis-induced kidney injury is mediated by the intrarenal renin-angiotensin system, for which urinary renin is a potential marker." (PMID 33382448, 2021). "Accordingly, we hypothesized that sodium bicarbonate supplementation reduces urinary renin excretion in patients with CKD and metabolic acidosis." (PMID 33382448, 2021).
adrenal pheochromocytomas (1 paper, 2016). "Four compounds are FN, i.e., a DA1/α1 agonist that induced pancreatic acinar cell adenoma, an imidazole PDE inhibitor that was associated with adrenal pheochromocytomas, a quinolone vasodilator, and a renin inhibitor that was associated with colon adenoma and carcinoma." (PMID 27790617, 2016).
Airway obstruction (1 paper, 2024). Obstruction of conducting airways of the lung. "During episodes of airway obstruction hypoxia stimulates the production of ET-1 and increases renin release from the kidneys." (PMID 39597901, 2024).
alcohol abuse (1 paper, 2013). The use of alcoholic beverages to excess, either on individual occasions ("binge drinking") or as a regular practice. "One of the mechanisms by which chronic alcohol abuse leads to oxidative stress includes activation of renin-angiotensin system in the lung." (PMID 23547562, 2013).
amnesia (1 paper, 2024). Pathologic partial or complete loss of the ability to recall past experiences ( AMNESIA, RETROGRADE) or to form new memories ( AMNESIA, ANTEROGRADE). "Bioactivities such as antioxidative, ACE-inhibitory, DPPIV-inhibitory, anti-amnesia, and renin-inhibitory activities were identified from the nine proteolyzed proteins." (PMID 39200521, 2024).
anaphylaxis (1 paper, 2012). An acute hypersensitivity reaction that occurs from exposure to an allergen. "Since this is the substrate for renin to generate AI this could be an important additional genetic factor in anaphylaxis." (PMID 23316249, 2012). "In our study, we have examined plasma renin, 25 hydroxy vitamin D, serum ACE levels, and ACE genotype in 119 controls, 49 atopics, and 120 subjects with prior IgE mediated anaphylaxis." (PMID 23316249, 2012).
benign prostatic hyperplasia (1 paper, 2023). A non-cancerous nodular enlargement of the prostate gland. "The studies reported in the literature demonstrated that components of the renin-angiotensin system are present in the prostate gland and that the expression of ACE and Ang-II are markedly increased in patients with benign prostatic hyperplasia (BPH)." (PMID 36836943, 2023).
brain cancer (1 paper, 2018). A primary or metastatic malignant neoplasm affecting the brain. "Renin-angiotensin system (RAS) in brain cancer represents a scarcely explored field in neuro-oncology." (PMID 30383794, 2018).
bruxism (1 paper, 2018). Excessive clenching of the jaw and grinding of the teeth. "In addition, spironolactone may decrease bruxism severity as a result of inhibition of the renin–angiotensin–aldosterone system and OSA reduction." (PMID 30301160, 2018).
Central hypothyroidism (1 paper, 2025). A type of hypothyroidism due to an insufficient stimulation of an otherwise normal thyroid gland. "The two MPD siblings showed primary amenorrhea, absent breast development and central hypothyroidism, while our patient had elevated cortisol, increased ACTH and renin." (PMID 40751525, 2025).
CHARGE syndrome (1 paper, 2019). CHARGE syndrome is a multiple congenital anomaly syndrome characterized by the variable combination of multiple anomalies, mainly Coloboma; Choanal atresia/stenosis; Cranial nerve dysfunction; Characteristic ear anomalies (known as the major 4 C's). "Several genes were reported only in syndromic cases; CHD7 (CHARGE syndrome), CR1 (van der Woude syndrome), EFNB1 (craniofrontonasal syndrome), KISS1R (Kallmann syndrome), MID1 (Opitz G/BBB syndrome), REN (van der Woude syndrome), and SOX9 (Pierre-Robin syndrome)." (PMID 31122291, 2019).
colon adenocarcinoma (1 paper, 2021). "In this study, we investigated whether cells from colon adenocarcinoma (CA) with a CSC-like phenotype express renin-angiotensin system (RAS) components, and the effect of RAS inhibitors on CA-derived primary cell lines." (PMID 34428252, 2021).
colorectal tumor (1 paper, 2021). "For example, ECM deposition in liver metastasis of colorectal tumor could enhance angiogenesis and anti-angiogenic therapy resistance, while inhibiting ECM deposition with drugs targeting the renin-angiotensin system could reverse resistance to anti-angiogenic bevacizumab." (PMID 34646782, 2021).
congenital hypothyroidism (1 paper, 2025). A thyroid hormone deficiency present from birth. "This is marked by decreased fetal renal REN expression, temporally decreased fetal pulmonary and renal ACE levels, and decreased postnatal ANGII concentrations following congenital hypothyroidism." (PMID 40939099, 2025).
dermatitis (1 paper, 2018). An inflammatory process affecting the skin. "In summary, we show that conditional deletion of RBP-J in renin-expressing cells leads to B-cell leukemia in Bl6 mice and dermatitis/MPD in SV mice." (PMID 30467111, 2018). "Animals from the SV background developed a severe dermatitis following conditional deletion of RBP-J within renin-expressing cells." (PMID 30467111, 2018). "Whereas deletion of RBP-J in renin-expressing cells of C57BL/6 mice leads to the development of B-cell leukemia, 129/SV mice develop dermatitis with a reactive, myeloproliferative phenotype." (PMID 30467111, 2018).
dissection (1 paper, 2024). The separation and isolation of tissues for surgical purposes, or for the analysis or study of their structures. "The occurrence of aortic dissection disrupts the hemodynamics of the body, leading to activation of the sympathetic nervous systems and renin-angiotensin-aldosterone." (PMID 38769137, 2024).
ductal carcinoma in situ (1 paper, 2006). "In ductal carcinoma in situ, positive (pro)renin staining was observed in the myoepithelial cells and fibroblasts as a disrupted band surrounding the ducts." (PMID 16755291, 2006).
Dyskinesia (1 paper, 2025). A movement disorder which consists of effects including diminished voluntary movements and the presence of involuntary movements. "Related to this, the brain renin–angiotensin system (RAS) and the RhoA/Rho kinase (ROCK) pathway, which are involved in dopaminergic neurodegeneration in PD as key mediators of oxidative stress and neuroinflammation, are also involved in dyskinesia development." (PMID 41154463, 2025).
emphysema (1 paper, 2022). "Finally, a negative association was found between serum levels of MMP-12 and renin, which were up-regulated in Cluster 1, and lower prevalence of emphysema." (PMID 36480517, 2022).
endometrial adenocarcinomas (1 paper, 2025). "We have previously shown that endometrial adenocarcinomas express prorenin mRNA and protein abundantly, so these low levels of REN mRNA were unexpected." (PMID 41303450, 2025).
endotoxemia (1 paper, 2023). "In endotoxemia, an activation of the renin-angiotensin system occurs and the biologically active angiotensin II level elevates; however, the vascular sensitivity to angiotensin decreases." (PMID 37327228, 2023).
erectile dysfunction (1 paper, 2021). Persistent or recurrent inability to achieve or to maintain an erection during sexual activity. "The change in erectile function was positively correlated with the cortisol levels and renin activity variation, suggesting that cortisol plays a role in erectile dysfunction in patients with PAI." (PMID 34202462, 2021).
familial juvenile hyperuricemic nephropathy type 2 (1 paper, 2024). Familial juvenile hyperuricemic nephropathy type 2 is a rare autosomal dominantly inherited disease of childhood characterized by hypoproliferative anemia, hyperuricemia and slowly progressing kidney failure due to dysregulation of the renin-angiotensin system (RAS). "ADKTD-REN, also referred to as familial juvenile hyperuricemic nephropathy type 2 (FJHN2), is associated with mutations in the REN gene, which leads to the synthesis of renin." (PMID 38254980, 2024).
Fibroadenoma (1 paper, 2006). A benign tumor of the breast characterized by the presence of stromal and epithelial elements. "In contrast, in fibroadenoma tissue, (pro)renin was now found to be localised in epithelial cells, as well as in myoepithelial cells, and stromal fibroblasts and connective tissue." (PMID 16755291, 2006).
gangrene (1 paper, 2023). Death of tissue, usually in considerable mass and generally associated with loss of vascular (nutritive) supply and followed by bacterial invasion and putrefaction. "Further leave-one-out sensitivity analysis for Mendelian randomization also showed robust causal relationship between renin-independent aldosteronism and LEAD or gangrene." (PMID 38124109, 2023).
glucose metabolism disorder (1 paper, 2025). "To further investigate the role of RAS in Tac-induced glucose metabolism disorder, we measured the levels of renin and Ang II in serum and renal tissue." (PMID 40495121, 2025).
Glycogen storage disease type Ia (1 paper, 2025).
Gynecomastia (1 paper, 2024). Abnormal development of large mammary glands in males resulting in breast enlargement. "He did not report recurrence of his gynecomastia nor mastodynia on spironolactone 37.5 mg daily, achieving an average home BP < 135/85 mm Hg, a satisfactory renin concentration of 12 mU/L, a stable average eGFR of 40 mL/min/m2, and normokalaemia (≤5.2 mmol/L)." (PMID 38887633, 2024).
Hartnup disease (1 paper, 2025). "This disruption likely contributes to Hartnup disease pathogenesis by impairing amino acid transport and may influence ACE2-mediated physiological functions beyond the renin-angiotensin system." (PMID 40852587, 2025).
HELLP syndrome (1 paper, 2023). A life-threatening condition that can potentially complicate pregnancy. "Notably, patients with HELLP syndrome did not exhibit the reduction in renin seen in pre-eclamptic patients." (PMID 37628909, 2023).
Huntington disease (1 paper, 2013). Huntington disease (HD) is a rare neurodegenerative disorder of the central nervous system characterized by unwanted choreatic movements, behavioral and psychiatric disturbances and dementia. "When the GSN gene set in the “hsa05040: Huntington's disease” pathway was tested against “GO:0030685∼ nucleolar preribosome”, “hsa00561: Glycerolipid metabolism” against “GO:0010033∼ response to organic substance” or “hsa04614: Renin-angiotensin system VS." (PMID 24086311, 2013).
hyperproinsulinemia (1 paper, 2004). "HI, hyperproinsulinemia, and hyperamylinemia synergistically activate RAS with subsequent increase in Ang II, renin, and aldosterone." (PMID 15507132, 2004).
Hypertonia (1 paper, 2016). A condition in which there is increased muscle tone so that arms or legs, for example, are stiff and difficult to move. "Another pharmacological alternative to influence the renin-angiotensin-aldosterone synthesis is the application of the relatively new renin inhibitor aliskiren that is also admitted for the treatment of hypertonia." (PMID 28025602, 2016).
infiltrating ductal carcinoma (1 paper, 2006). "In infiltrating ductal carcinoma grade II, (pro)renin staining was absent from the majority of fibroblasts whereas some epithelial cells showed positive staining." (PMID 16755291, 2006).
interstitial lung disease (1 paper, 2022). A diverse group of lung diseases that affect the lung parenchyma. "A study suggests a possible harmful role of renin-angiotensin inhibition in interstitial lung disease." (PMID 38046538, 2022).
invasive carcinoma (1 paper, 2006). A carcinoma that is not confined to the epithelium, and has spread to the surrounding stroma. "As Ang II has numerous functions in epithelial and other tissues, including the regulation of mitosis and tissue differentiation, the observation that (pro)renin transcription apparently fails in invasive carcinoma, crucially suggests that here Ang II is not available to maintain these functions." (PMID 16755291, 2006).
leiomyoma (1 paper, 2023). A well-circumscribed benign smooth muscle neoplasm characterized by the presence of spindle cells with cigar-shaped nuclei, interlacing fascicles, and a whorled pattern. "The involvement of many proteins such as FN1, COL1A1, BMP7, CCND1, EZH2, HMGA2, AhR, and E2F1 shown in the protein–protein interaction networks are well known in leiomyoma pathogenesis; others, such as SOX2, REN, PPARG, ABCB1, and NR3C1 are novel and require further investigation." (PMID 36835153, 2023).
lip squamous cell carcinoma (1 paper, 2017). "We investigated the expression of the renin–angiotensin system (RAS) by cancer stem cell (CSC) subpopulations we have identified in moderately differentiated lip squamous cell carcinoma (MDLSCC)." (PMID 28634582, 2017).
microangiopathic hemolytic anemia (1 paper, 2012). "The laboratory evaluation revealed remarkably high plasma renin activity in association with microangiopathic hemolytic anemia, and the anti-RNA polymerase III antibody assessment was positive." (PMID 22738362, 2012). "A laboratory evaluation revealed the following: a blood urea nitrogen (BUN) level of 71 mg/dl (25.3 mmol/L), a serum creatinine level of 4.69 mg/dl (414.6 μmol/L) and a plasma renin activity above 20 ng/ml/hr (above 5.56 ng/L/s, normal range 0.9–2.9 ng/ml/hr) with microangiopathic hemolytic anemia." (PMID 22738362, 2012).
mineral bone disorders (1 paper, 2025). "Therapies, which could benefit autonomic performance (exercise training,pharmacological modulation of the renin-angiotensin system and control of mineral bone disorders) could help decrease the cardiovascularrisk of CKD patients." (PMID 41170053, 2025).